MTOR (mechanistic target of rapamycin kinase)
Diseases named in the same sentence as MTOR in open-access papers (continued):
Sharing a sentence is not in itself a finding about the gene and the disease.
tumor (continued). "The results indicated that compared with control cells, AKT and mTOR phosphorylation was significantly increased following YTHDF2 overexpression, which is crucial for tumor progression." (PMID 34996459, 2022). "Many inhibitory effects of metformin on tumor growth through AMPK and mTOR signalings were confirmed using different mouse models of cancer." (PMID 35574410, 2022). "In our previous study using tissue microarray data from the WCHS participants, phosphoprotein expression of MTOR, AKT1, and S6K1 were consistently lower in patients with a higher grade tumor, larger tumor, more advanced disease, or TNBC." (PMID 35608730, 2022). "It is, therefore, assumed that AKT/mTOR as well as CDK-Cyclins cross-talk with integrins, such that both tumor growth and metastatic settlement occur in a coordinated manner." (PMID 35626034, 2022). "Loss of function of VHL leads to an accumulation of HIF-α and mimics or aggravates a hypoxic situation in the tumour, leading to an increase in PI3-K/PKB/mTOR signalling and tumour progression." (PMID 36551652, 2022). "For example, PTEN, a tumor suppressor, blocks the activation of PI3K/AKT/mTOR pathway by inhibiting the transition from PIP2 to PIP3." (PMID 35694243, 2022). "SB365 (PSD) can significantly inhibit tumor growth in an HCC xenograft model and induce apoptosis by effectively suppressing the phosphorylation of PI3K downstream factors, such as Akt, mTOR and p70S6K both in vitro and in vivo." (PMID 35606807, 2022). "It has been confirmed by a study that downregulated FDFT1 is related to late tumor progression and worse prognosis in CRC, and FDFT1 suppresses the tumorigenesis through negative regulation of AKT/mTOR/HIF1α signaling pathway." (PMID 36160009, 2022). "Several tumor suppressor genes involved in upstream inhibition of mTOR signaling, including PTEN, TSC1, and TSC2, stimulate autophagy; conversely, mTOR-activated oncogene products such as class I PI3K and Akt inhibit autophagy." (PMID 35456001, 2022). "While PTEN reduces tumor growth and affects PI3K/Akt/mTOR signaling pathway, PDCD4 is involved in many cellular functions and behaviors such as tumor growth, apoptosis, invasion and cell transformation." (PMID 35682901, 2022). "PTEN acts as a tumor suppressor gene through the action of its phosphatase protein product, which negatively regulates the PI3K/AKT/mTOR pathway." (PMID 35457244, 2022). "In summary, our results show that G-MDSCs initiates immunosuppressive functions in the peripheral blood of tumor-bearing mice and that G-CSF participates in the acquisition of G-MDSC immunosuppressive functions by activating the PI3K-Akt/mTOR pathway." (PMID 35013108, 2022). "The mTOR pathway can also modulate epithelial-mesenchymal transition (EMT), thus being a promoter of tumor migration." (PMID 35200568, 2022). "In various tumours, the activation of the PI3K/AKT/mTOR pathway promotes the initiation and nucleation of autophagy." (PMID 35883139, 2022). "Contrarily, in differentiated cancer cells, FMD stimulates starvation escape pathways, including mTOR, PI3K/AKT, and CDK4/6, thus providing therapeutic targets that can lead to tumour regression with low toxicity." (PMID 36077812, 2022). "It was determined that YKL-40 participates in the regulation of phosphatidylinositol 3 kinase (PI3K)/AKT/mTOR pathway or Ras/Raf/MEK/ERK cascade, which is related to tumor survival, transformation, invasion, and metastasis." (PMID 36428997, 2022). "Accordingly, tumor cells showed lower levels of phosphorylated(p)-S6RP, p-Akt and p-mTOR when treated with GNE-317 or pictilisib." (PMID 34216217, 2022). "In an RCC xenograft mouse model, inhibition of mTOR and blocking of PD-L1 enhanced CD8 + cell lysis and tumor suppression." (PMID 36550835, 2022).
tumor (continued). "Tumor cells can escape drug-induced growth inhibition and death through the PI3K/Akt/mTOR pathway, whereas the PI3K/Akt/mTOR pathway activates the autophagic pathway, which in turn protects tumor cells." (PMID 36551309, 2022). "The PC mice had abundant tumours, markedly elevated proliferation markers (survivin/CCND1) and PI3K/Akt/mTOR, and reduced p21/PTEN/cytochrome C/caspase-3 and apoptosis." (PMID 35326689, 2022). "Increased intracellular cholesterol esters are associated with the growth and invasion of a variety of tumors, while oxidative stress can activate multiple downstream tumor-related pathways, such as the PI3K/AKT/mTOR signal pathway." (PMID 36033523, 2022). "Overall, our data suggest that deregulated Akt1/mTOR signaling in ERMS cells, promoting an aggressive tumor phenotype, can become the Achilles’ heel for the tumor if the availability of some nutrients or their metabolism is disrupted." (PMID 36139434, 2022). "Inhibitors of PI3Kγ or mTOR as well as agonists of CD40, TLR4, -7, -8, or -9 can repolarize macrophages towards a proinflammatory phenotype promoting tumor suppression in preclinical studies." (PMID 36237314, 2022). "Inhibition of the mTOR/PI3K pathway and induction of caspase-dependent apoptosis can improve liver function, oxidative DNA damage and tumor-specific markers, thus counteracting the carcinogenic effect of diethylnitrosamine." (PMID 35836300, 2022). "This combination enhanced attenuation of the PI3K/Akt/mTOR pathway more than EGFR inhibitor alone, including enhancing the tumour cell killing effect, which is unsurprising given the positive role of CK2 in phosphorylating prosurvival Akt." (PMID 35214064, 2022). "In conclusion, HCG22 exerted anti-tumor properties in OSCC by inhibiting the Akt, mTOR, and Wnt/β-catenin pathways." (PMID 35525925, 2022). "Another mechanism of increased proliferation is through the induction of B. fragilis–associated long noncoding RNA 1 (BFAL1), which activates the Ras homolog in the mammalian target of rapamycin (mTOR) pathway, and increases CRC tumor growth." (PMID 35166235, 2022). "In animal models of PNENs, treatment with mTOR inhibitor led to modifications to the matrix consistency of the TME and ultimately blocked the dissemination of the tumor and the onset of metastasis." (PMID 35884539, 2022). "Another miRNA with tumor-promoting activity is miR-208a, which promotes the activation of Akt/mTOR in NSCLC cells through p21, and then promotes the proliferation of tumor cells." (PMID 36144639, 2022). "The miR-96-3p up regulation increased tumor cell invasion and TC metastasis by regulating SDHB/AKT/mTOR pathway." (PMID 35659780, 2022). "Although the efficacy of mTOR inhibitors alone is limited, mTOR inhibitors exert anti-HCC tumor activity in synergy with anti-PD-1 therapy." (PMID 36686771, 2022). "Activation of AMPK increases the expression levels of Beclin-1 and LC3-II but decreases p-mTOR and p-ULK1 in tumor cells." (PMID 36362079, 2022). "In VEGF-induced tumor cells, the PI3K/AKT/mTOR pathway, which is the downstream pathway of VEGFR, can be activated to mediate the adhesion, proliferation, and migration of endothelial cells." (PMID 36213383, 2022). "In the in vitro experiments, they showed that total flavonoid aglycone extracted exhibited an anti-tumor activity, and induced apoptosis and autophagy in PC cell lines through the PI3K/Akt/mTOR signaling pathway." (PMID 35276978, 2022). "Research findings demonstrated that glycyrrhizic acid, a bioactive compound in licorice, induces apoptosis in TF-1 leukemia cells via blocking Akt, mTOR, and STAT3 phosphorylation signaling in tumor tissues." (PMID 36428613, 2022). "FGFR1 promotes tumor growth and proliferation by activating growth and nutrient signaling via PI3K and mTOR activation." (PMID 35626002, 2022).
tumor (continued). "Phosphatase and tensin homolog (PTEN) acts an important tumor suppressor and a negative regulator of cell growth and survival signaling by antagonizing the phosphoinositide 3-kinase (PI3K)/AKT/mammalian target of rapamycin (mTOR) cascade." (PMID 36077184, 2022). "In tumor cells, autophagy is mainly regulated by the AMP-activated protein kinase (AMPK) and mammalian target of rapamycin (mTOR) pathways." (PMID 36408240, 2022). "Extracellular citrate administration in tumor cells induces activation of the DNA damage response, MAPK, and mTOR signaling pathways." (PMID 34747157, 2022). "PTEN is a tumour suppressor gene and negatively regulates the growth-promoting PI3K/AKT/mTOR signal transduction pathway." (PMID 35326573, 2022). "Mounting evidence has unveiled the promotion effect of numerous anti-tumor drugs on apoptosis and autophagy through the suppression of AKT/mTOR signaling." (PMID 35485300, 2022). "Overexpression of MAL2 resulted in the hyper-activation of the MAPK/mTOR signaling pathway in NSCLC cells, leading to active ribosome biogenesis which promoted cell proliferation and tumor growth." (PMID 35437691, 2022). "Our data provide new insights into the tumour‐suppressive role of PB1 and also links with glycolysis, mTOR and HIF1α in ccRCC." (PMID 35672925, 2022). "The authors showed a correlation between clinical outcomes and viperin expression levels in multiple cancer tissues and proposed that viperin expression was upregulated in the tumor microenvironment via the JAK/STAT and PI3K/AKT/mTOR/HIF-1α pathways." (PMID 36519538, 2022). "Previous studies indicate that oncoproteins, such as Ras, Akt, and mTOR, regulate the PPP in tumor cells to increase cell survival and proliferation." (PMID 35806424, 2022). "miR-19b specifically targeted the tumor-suppressive co-chaperone TSC1 and activated the mTOR pathway, which promoted cancer stem cell (CSC) proliferation." (PMID 35625953, 2022). "Two patients received only cytokines prior to tumour sampling, while others were pretreated with VEGF‐targeted therapy (n = 36), mTOR inhibitors (n = 15) or immune checkpoint inhibitors (n = 7)." (PMID 35231161, 2022). "This coincided with the activation of many signals related to tumor development, such as the MYC signaling pathway, E2F target, oxidative phosphorylation, interferon response, and mTOR signaling pathway." (PMID 36569894, 2022). "Among them, CCL2 activates the PI3K/Akt/mTOR signaling pathway to promote formation of endocrine resistance feedback loops in the TME, which improves tumor growth." (PMID 35672862, 2022). "Another report shows the degradation metabolism of BCAA is inhibited in a variety of tumor types, promoting the accumulation of intracellular BCAA, the activation of mTOR signaling pathway, and the occurrence and development of tumors." (PMID 35785192, 2022). "We investigated the hypoxic tumor microenvironment, finding that SOCS5 promoted the invasion and migration of HCC cells by activating the PI3K/Akt/mTOR-HIF-1α signaling axis." (PMID 36319626, 2022). "Down-regulation of the PI3K/AKT/mTOR/MMP-2/9 pathway can inhibit migration and invasion of tumour cells." (PMID 35840921, 2022). "Cyclosporine substitution by mTOR inhibitor decreased the incidence of NMSC, while even only adding sirolimus to cyclosporine therapy slowed down tumor growth and progression." (PMID 35505648, 2022). "Metformin-activated AMPK/mTOR signal transduction pathway can reduce the expression and stability of hypoxia-inducible factor-1α (HIF-1α) in tumor cells." (PMID 36397350, 2022). "It is also known that miR-132 represses the Akt/mTOR signaling pathway, which is activated by DMBA and involved in promoting tumor formation." (PMID 35326471, 2022). "Western blot analysis of the expression of KIT-mediated signalling pathways in tumour tissues demonstrated that cabozantinib treatment also decreased p-KIT, p-STAT3, p-AKT, p-mTOR, and p-ERK1/2 expression levels in vivo." (PMID 33833412, 2022).
tumor (continued). "During mTOR/AKT/PI3K activation, 4E-BP1 is phosphorylated, which frees and activates eIF4E and stimulates translation and tumor growth in vivo." (PMID 35626002, 2022). "The majority of the pathways that support immune function are well-established pathways, such as the mTOR and PI3k pathways, with increasingly selective agents available for sophisticated tuning of the immune cells in the TME to eradicate tumor cells." (PMID 34239083, 2022). "This showed the anti-tumor effect of CIK cells in proliferation, apoptosis, the number of invasive cells in CRC, and the possible role of the AMPK/Akt/mTOR pathway." (PMID 35346234, 2022). "mTOR-mediated inhibition of autophagy, however, sensitized tumors cells to such an extent that tumors could be eradicated in mice using well-tolerated doses of glycolysis inhibitors, arguing that autophagy defects in tumor cells can open a therapeutic window for metabolic cancer treatments." (PMID 35681458, 2022). "Several studies have shown that abnormal activation of PI3K/AKT/mTOR and Ras/RAF/MAPK pathways are beneficial to tumor cell proliferation, migration, and invasion; thus, acting as an important entity in tumor development and drug resistance." (PMID 35313850, 2022). "The down-regulation of AKT, mTOR, Rictor, and Raptor in TCCSUP, T24, RT112, and RT4 cells corresponds well with the diminished tumor growth and proliferation capacity seen with SFN." (PMID 36230603, 2022). "HOTAIR upregulation was identified in an ovarian cancer cell model, and it was found to increase tumor progression and promote tumor aggressiveness and metastasis via activation of the PI3K/AKT/mTOR pathway." (PMID 35813070, 2022). "In these mice, combined treatment with cabozantinib, which targets c-Met, and the dual mTOR inhibitor MLN0128, which targets activated β-catenin effectors, leads to tumor regression, whereas cabozantinib or MLN0128 monotherapy does not." (PMID 35166233, 2022). "GSEA revealed 15 pathways enriched significantly in epithelial cells of residual tumor, including inflammatory response, interferon alpha and interferon gamma response, as well as PI3K/Akt/mTOR signaling and mTORC1 signaling pathways." (PMID 35784460, 2022). "The combination of mTOR and GLS inhibitors was shown to synergistically reduce GBM tumor formation in a preclinical setting." (PMID 35163279, 2022). "AMPK can inhibit cell growth by inhibiting mTOR/P70S6K signaling, thereby exerting anti-tumor effects." (PMID 36588732, 2022). "The dysregulational mitochondrial function, oxidative stress, PI3K/AKT/mTOR, and AMP-activated protein kinase (AMPK) signaling pathways all play important roles in metabolism reprogramming in tumor cells." (PMID 36145507, 2022). "AKT is on the central node of PI3K/AKT/mTOR pathway and inhibition of AKT induces HRD in the tumor cells." (PMID 35419627, 2022). "Treatment with vandetanib significantly decreased the levels of p‐PI3K P85/P55 and the phosphorylation of AKT, MTOR, MEK1/2 and ERK1/2 and increased the phosphorylation of P38 in K562 tumor tissues." (PMID 35689424, 2022). "GBM tumor cells promote M2 GAM polarization by activation of STAT3, NF-κB, Wnt-3a, and mechanistic target of rapamycin (mTOR), resulting in upregulation of IL-10 levels." (PMID 35572545, 2022). "These include the promotion of tumor progression (e.g., the facilitation of tumor cell migration and invasion), the suppression of CD4-positive T cells, and the activation of the mTOR function that stimulates the proliferation of AML cells." (PMID 36142442, 2022). "LKB1-AMPK (AMP-activated protein kinase) pathway is considered to be another tumor suppressor, and the activation of AMPK can also inhibit tumor cell growth and metabolism by regulating mTOR activity." (PMID 36124026, 2022). "The expression of p-mTOR S2448, p-4E-BP1(T37/46), p-mTOR S2481 and Rictor were decreased in tumor of SR group." (PMID 35145073, 2022).
tumor (continued). "The routine scheduling of classic targeted therapies commonly completely underestimates the diversity of tumor systems states and the important fact that activity profiles of single targeted drugs may context-dependently decisively change, as to be exemplified with mTor inhibitors." (PMID 35814409, 2022). "LINC00674 contributed to the malignant behaviors of tumor cells, possibly by activating the NADPH oxidase 1 (NOX1)/mTOR signaling pathway in HCC." (PMID 36118523, 2022). "In tumor cell lines, miR-27a blocked AMPK and enhanced mTOR signaling, promoting aerobic glycolytic metabolism and supporting biomass production." (PMID 35337261, 2022). "It specifically showed that apoptin targets PKM2 inhibits glycolysis and tumor cell proliferation, and promotes autophagy and apoptosis by regulating the PKM2/AMPK/ mTOR pathway." (PMID 36284386, 2022). "In addition, MSCs also reprogram toward CSCs, due to the aberrant changes of tumor microenvironments, which leads to the tumor development through the increased production of Oct4, Sox2, Nanog and the activation of Hedgehog, Wnt, Akt/mTOR, and NF-kB signaling pathways." (PMID 35251985, 2022). "The hotspot mutation H1047R in PI3KCA, frequently detected in BRCA, activates the PI3K/AKT/mTOR pathway and promotes BRCA tumor formation." (PMID 35707265, 2022). "Different authors have demonstrated that high expression of ADRA2A was associated with a better prognosis, and its overexpression was capable of suppressing tumor invasion and growth through inhibition of the PI3K/Akt/mTOR pathway." (PMID 36075937, 2022). "PTEN, a tumor suppressor, acts as a negative regulator of the phosphatidylinositol 3-kinase/AKT/mTOR pathway, playing a critical role in tumorigenicity." (PMID 35241735, 2022). "The ability of ILK to regulate phosphorylation of components of the phosphoinositide 3-kinase/mammalian target of rapamycin (PI3K/mTOR) signaling complex, such as Akt and Rictor, is critical in promoting tumor cell survival." (PMID 35804980, 2022). "Both mTOR inhibition and AMPK activation are prominent signaling mechanisms regulating autophagy in tumor cells." (PMID 35211405, 2022). "The addition of mTOR inhibitor to palbociclib markedly reduced p-Rb (P = 0.017) and cyclin D1 (P < 0.001) levels in these S6K1-overexpressed tumours." (PMID 36042494, 2022). "The function of PTEN is well established, being the tumor suppressor commonly inhibited in tumors and one of the main negative regulators of the PI3K/AKT/mTOR pathway." (PMID 36224313, 2022). "CXCR4 knockdown resulted in a reduction in CSCs and EMT formation and enhancement of chemotherapy sensitivity in tumor cells, which was further advanced by blocking CXCR4-PI3K/Akt/mTOR signaling." (PMID 35681259, 2022). "AKT1, commonly known as fuselage 1 on v-akt murine thymoma virus tumor gene, is an oncogene and is a member of the PI3K/Akt/mTOR pathway." (PMID 36286049, 2022). "PI3K/mTOR and its downstream targets, 4EBP1 and P70S6K, are important factors for tumor cell survival and proliferation." (PMID 35311154, 2022). "We found that BP can repress the mTOR pathway by downregulating MLST8 and EIF4EBP1 to inhibit AML cell proliferation and in vivo tumor growth." (PMID 35579750, 2022). "In kidney cancer, the activation of Axl by Gas6 or autocrine signaling leads to tumor cell growth, metastasis, invasion, EMT, angiogenesis, and drug resistance, mainly in a PI3K-Akt-mTOR dependent manner." (PMID 35892875, 2022). "Everolimus is a mechanistic/mammalian target of rapamycin (mTOR) inhibitor and is thought to inhibit tumor growth directly and indirectly by suppressing the proliferative signals of the PI3K/AKT/mTOR signaling pathway." (PMID 35506423, 2022). "Anlotinib targeted FGFR3 in the treatment of OSCC and inhibited tumor cell proliferation and promoted apoptosis by inactivating the FGFR3/AKT/mTOR signaling pathway." (PMID 36167542, 2022).